ALK (ALK receptor tyrosine kinase)
Diseases named in the same sentence as ALK in open-access papers (continued):
Sharing a sentence is not in itself a finding about the gene and the disease.
neuroblastoma (continued). "Although the standard route for the evaluation of novel compounds is through early phase clinical studies in relapsing or treatment-refractory disease, there is strong preclinical rationale for the combination of ALK inhibition with up-front chemotherapy in ALK-positive neuroblastoma patients." (PMID 35582571, 2019). "Another study focused more specifically on clinical trials of ALK inhibitors in neuroblastoma." (PMID 30813562, 2019). "Treatment with crizotinib in pediatric cancers such as NSCLC and IMT has shown an encouraging and efficient effect for tumors which harbor ALK fusion oncogenes, however, responses were less encouraging for treatment of pediatric neuroblastoma patients with crizotinib." (PMID 31334113, 2019). "Genomics analyses of relapsed neuroblastomas indicate that such treatments could include inhibition of ALK and the RAS-MAPK pathway, YAP inhibition and/or pathways involved in EMT." (PMID 28924803, 2018). "Overall, the kinome-wide RNAi screen identified the PI3K pathway to be involved in HDAC8 inhibitor-mediated anti-neuroblastoma effects and identified additional druggable RTKs, such as ERBB2 and ALK, as targets to sensitize neuroblastoma to HDAC8 inhibitor treatment." (PMID 29515255, 2018). "This trial had a dedicated phase 2 cohort for individuals with ALK aberrant neuroblastoma." (PMID 30326621, 2018). "Furthermore, entrectinib, small molecule inhibitor of major neuroblastoma pathogenic marker—anaplastic lymphoma kinase (ALK), exerts pro-autophagic effects on SH-SY5YF1174L neuroblastoma cells." (PMID 30027525, 2018). "It has been recently shown that ALK expression is associated with a less differentiated state of neuroblastic tumors, and the incidence of ALK overexpression in neuroblastoma is significantly higher than in more differentiated ganglioneuroblastoma and ganglioneuroma." (PMID 30116755, 2018). "Furthermore, several studies have shown that aberrant ALK signaling in neuroblastoma cells regulates MYC and MYCN transcriptional initiation and protein stability." (PMID 29507657, 2018). "Focal aberrations affect genes known to be involved in neuroblastoma, such as ALK and LIN28B." (PMID 30375995, 2018). "Moreover, two novel bona fide neuroblastoma oncogenes have been identified, ALK and LIN28B, that are sufficient to drive tumor formation when overexpressed in the neural crest or seem to increase the oncogenic potential of MYCN overexpression." (PMID 29492199, 2018). "Recently, two neuroblastoma mutants, F1174L and R1275Q, have been determined to cause ALK activation without phosphorylation on Y1278." (PMID 30004444, 2018). "In addition to activating wild type ALK, FAM150A/B promote “superactivation” of activated ALK mutants from neuroblastoma." (PMID 29455675, 2018). "Germline ALK mutations have incomplete phenotypic penetrance, meaning that not all affected individuals will develop neuroblastoma." (PMID 30200332, 2018). "Currently, the most druggable target for neuroblastoma is anaplastic lymphoma kinase (ALK)." (PMID 30326621, 2018). "In addition to neuroblastoma, ALK amplification and ALK copy number gain have been found in other cancers, such as rhabdomyosarcomas." (PMID 30400214, 2018). "As observed in ALK rearrangements, ALK point mutations have been described in number of cancers (i.e., anaplastic thyroid cancer [ATC], IMT and NSCLC), although less frequently than in neuroblastoma." (PMID 29495603, 2018). "To expand the panel of investigated cell lines, we determined the ALK expression status of five neuroblastoma cell lines, a cell line from a non-neuroblastoma pediatric embryonal tumor (RD, rhabdomyosarcoma), and a non-malignant but proliferative fibroblast line from an infant donor (VH7)." (PMID 29515255, 2018). "Aberrant activation of ALK activity plays a crucial oncogenic role in neuroblastoma." (PMID 30400214, 2018).
neuroblastoma (continued). "A connection between ALK and MYC has been observed in neuroblastoma, where ALK gain-of-function mutations are more frequent in MYCN amplified tumors and activation of full length ALK increases mRNA, protein expression, and transformation potential of MYCN in neuroblastoma cell lines." (PMID 29507657, 2018). "Although ALK translocations are not typically seen in neuroblastoma, approximately 14% of children with high-risk neuroblastoma have tumors that harbor either ALK mutations or amplification." (PMID 30326621, 2018). "Other genetic mutations, such as SNPs in the ALK and BARD1 genes and copy number polymorphism of NBPF23, may also have a role in neuroblastoma development." (PMID 30285664, 2018). "Though many cancers can be attributed to genetic changes induced by hereditary predisposition, as described in neuroblastoma for the PHOX2B and ALK genes, others may be the result of lifestyle or environmental factors." (PMID 30200332, 2018). "We aimed to establish MYCN and ALK droplet digital PCR for the routine assessment of copy number status from sequential neuroblastoma blood and bone marrow samples to assist risk stratification and detection of cancer progression via MYCN- or ALK-dependent tumor-promoting subpopulations." (PMID 29156716, 2017). "In addition, the IC50 values for the four ALK inhibitors in the F1174L neuroblastoma cell lines were 10 to 100-fold higher than the IC50 values in Ba/F3 cells expressing EML4-ALK F1174L mutant." (PMID 28425916, 2017). "Overall, the responses of relapsed neuroblastoma with known ALK-activating mutations to crizotinib or ceritinib were not optimal for such targeted therapies." (PMID 28425916, 2017). "To test this hypothesis, we exposed the four neuroblastoma cell lines that harbor ALK aberrations to combinations of ceritinib and CGM097." (PMID 28425916, 2017). "For example, T cells expressing a CAR incorporating a scFv of the ALK48 mAb linked to a 4-1BB-CD3ζ signaling domain elicited ALK-expressing tumor lysis and produced IFN-γ upon antigen stimulation, but limited anti-tumor efficacy was observed in xenograft models of human neuroblastoma." (PMID 29189709, 2017). "Finally, ALK mutations and MYCN amplification co-occur in a subset of neuroblastoma patients, emphasizing the need to target both oncogenes." (PMID 28425916, 2017). "Altogether, these studies interestingly suggest that depending on the ALK gene status, the autophagy that is activated following ALK inhibition could lead to opposite outcomes, i.e., cytoprotection in ALK-mutated neuroblastoma or cytotoxicity in ALK amplified or wild-type NB." (PMID 29186933, 2017). "ALK-positive neuroblastoma mutants fall into three classes: gain-of-function (GOF) ligand independent mutations, ligand dependent mutations which are not constitutively active and require activation with either FAM150 (AUG) ligands or agonist antibodies, and finally kinase-dead mutations." (PMID 28030793, 2017). "Our results with 106 primary neuroblastomas reveal that TIAM1 has a higher incidence of variants (11%), and they significantly associate as an independent variable with better outcome, even in the concomitant presence of MYCN amplification or ALK mutation." (PMID 28423360, 2017). "ALK gain was reported to occur in ∼15–20% of primary neuroblastomas." (PMID 29156716, 2017). "However, as the mutation/amplification rate in neuroblastoma cases is relatively low, our knowledge regarding the genetic profiles of neuroblastomas with ALK abnormalities is still limited." (PMID 29296183, 2017). "ALK diploid status was also confirmed in all neuroblastoma cell lines using cfDNA." (PMID 29156716, 2017). "Combinatorial therapies that target other signaling pathways in addition to ALK may be required to improve the effectiveness of ALK inhibitors in neuroblastomas that harbor ALK aberrations." (PMID 28425916, 2017).
neuroblastoma (continued). "In this report, we have validated immunoassays to detect ALK and phosphorylated ALK in vitro, successfully applied them to an in vivo model of neuroblastoma, and demonstrated a quantitative difference in on‐target pharmacodynamic changes between a first‐ and second‐generation ALK inhibitor." (PMID 28432815, 2017). "In the clinical studies of crizotinib and ceritinib in pediatric patients with ALK-driven neuroblastoma, most tumors harboring R1275Q-mutated ALK did not respond to the treatments even although cells with the R1275Q mutation are sensitive to both drugs." (PMID 28425916, 2017). "In addition, several groups have reported a strong significant trend between high ALK expression levels and poor outcome in patients with neuroblastomas." (PMID 29296183, 2017). "ALK copy numbers detected using cfDNA also significantly correlated (Spearman’s correlation coefficient r = 0.8143) with copy numbers measured in corresponding gDNA from all 15 neuroblastoma cell lines assessed." (PMID 29156716, 2017). "When compared to the Ba/F3‐transduced cell lysates, it was apparent that detection and therefore quantification of phosphorylated ALK is challenging in the neuroblastoma cell panel by western blotting as bands were only clearly visible for pY1278 and pY1586 ALK in CLB‐GA and LAN‐5 lysates." (PMID 28432815, 2017). "Since the FAM150 (AUG) ligands are able to drive further activation of ALK mutants from neuroblastoma, dysregulation of the ALK ligands may potentially play a role in neuroblastoma." (PMID 28030793, 2017). "Therefore, the proportion of ALK-positive neuroblastoma patients benefits from Crizotinib is limited." (PMID 28055978, 2017). "Together ALK and RAS mutations implicate mitogen/extracellular signal-regulated kinases (MEK1/2) and extracellular signal-regulated kinases (ERK1/2) in survival and proliferation of neuroblastoma." (PMID 28602975, 2017). "In addition to genetic alterations of ALK, elevated ALK expression levels have been previously reported in two-third of primary neuroblastoma cases." (PMID 29296183, 2017). "Multiple epidemiological studies on the distribution of ALK mutations in relation to MYCN status and other genomic parameters have revealed the co-occurrence of ALK mutations and MYCN amplification in neuroblastoma, indicating that additional oncogenic drivers exist other than ALK." (PMID 28425916, 2017). "ALK amplification is reported in 2–5% of primary neuroblastomas." (PMID 29156716, 2017). "Given that N-myc acts as a key effector of PI3K-meditated VEGF expression in neuroblastomas, it appears that positive feedback loops among N-myc, ALK, and Akt pathways may exist in perivascular GBM cells, leading to deregulation of VEGF expression." (PMID 28837676, 2017). "Furthermore, we recapitulate a number of compounds targeting proteins associated to neuroblastoma: MYCN (direct and indirect inhibitors) and downstream targets, Trk, ALK and its downstream signalling pathways." (PMID 28178969, 2017). "Neuroblastoma may develop when neuroblasts evade this cell death signaling (e.g., through loss of CASPASE-8 or activation of ALK), and subsequently adopt tumorigenic phenotypes." (PMID 28035989, 2016). "Aberrant ALK activity occurs in about 5-7% of neuroblastoma cases but this percentage increases significantly in the relapsed patient population, thereby adding weight to the clinical relevance of ALK in neuroblastoma pathogenesis." (PMID 27049722, 2016).
neuroblastoma (continued). "However, aberrant ALK in neuroblastoma typically presents as full-length membrane-bound receptor protein." (PMID 27732954, 2016). "Collectively, this study provides insight into the downstream signaling pathways activated by membrane-bound full-length ALK in neuroblastoma, and demonstrates theoretical support for promoting the clinical use of ALK-specific inhibitors in neuroblastoma patients with aberrant ALK signaling." (PMID 27732954, 2016). "Our data clearly demonstrate that JNKs function as common oncogenic proteins in neuroblastoma independent of the ALK variant present." (PMID 27732954, 2016). "Additionally, we observed significantly decreased phosphorylation levels at multiple ALK-regulated sites following Crizotinib treatment of the ALK-amplified neuroblastoma cell line NB1." (PMID 27732954, 2016). "ALK receptor tyrosine kinase has been shown to be a therapeutic target in neuroblastoma." (PMID 26786851, 2016). "Thus, brigatinib inhibits ALK activity in ALK addicted neuroblastoma cell lines more efficiently than crizotinib and displays a lack of toxicity at the cellular level." (PMID 27049722, 2016). "We also included analysis of the ALK-G1269A mutant, which has so far not been observed as a neuroblastoma mutation but has been described as a more resistant mutation arising in EML4-ALK from NSCLC patients treated with crizotinib." (PMID 27049722, 2016). "Interestingly, we also identified differences in ALK phosphorylation substrates in neuroblastoma cells." (PMID 27732954, 2016). "This suggests that ALK may play a more important role in the development of neuroblastoma than previously thought." (PMID 27483357, 2016). "We examined PF-06463922 activity in ALK-driven neuroblastoma models in vitro and in vivo." (PMID 27483357, 2016). "However, brigatinib inhibits ALK addicted neuroblastoma cell line proliferation with roughly 2 to 3-fold lower IC50 values compared with crizotinib." (PMID 27049722, 2016). "For example, these technologies recently led to the identification of frequent mutations in anaplastic lymphoma kinase (ALK) gene in both familial and sporadic neuroblastoma cases; as a result, ALK inhibitors are currently in clinical trials with promising preliminary results." (PMID 28035989, 2016). "Using both Sanger and targeted deep sequencing, this study describes the identification of distinct ALK mutations in these paired cell lines, including the rare R1275L mutation, which has not previously been reported in a neuroblastoma cell line." (PMID 27888620, 2016). "One such inhibitor, the first 3rd generation ALK (and ROS1) inhibitor PF-06463922 (lorlatinib), exhibits increased potency against F1174L, 1151Tins, I1171T and G1269A in preclinical EML4-ALK models, with impressive anti-tumour activity observed in xenograft neuroblastoma models harboring F1174L." (PMID 27009859, 2016). "Thus, in addition to the potent inhibition seen in cell culture models and in vitro kinase assays, PF-06463922 exhibits robust activity towards tumor growth in a transgenic ALK-driven mouse model of neuroblastoma." (PMID 27483357, 2016). "This low response in neuroblastoma patients may reflect the heterogeneity of the disease, and may also reflect the need for more potent ALK inhibitors in this tumor type." (PMID 27049722, 2016). "Although it has only been described in EML4-ALK fusions, we have included ALKG1269A here in the context of full-length ALK, motivated by the potential future relevance for neuroblastoma patients that may be treated with ALK inhibitors." (PMID 27483357, 2016). "Multiple ALK point mutations have been identified in neuroblastoma, however, not all of them are classified as gain-of-function mutations, as some of the mutations are kinase dead and some seem to behave (at least in terms of activation) as wild type ALK." (PMID 27049722, 2016). "Low copy number gains and amplifications of ALK have also been reported in neuroblastoma." (PMID 27888620, 2016).
neuroblastoma (continued). "ALK gene amplification is also involved in neuroblastoma tumorigenesis." (PMID 27732954, 2016). "Thus, in the context of neuroblastoma, a number of approaches are actively being explored for therapeutic intervention, with evaluation of new ALK inhibitors a high priority." (PMID 27049722, 2016). "An additional alternative hypothesis takes into account the locations of ALK mutations in therapy-induced resistance mutations of NSCLC and primary therapy-naïve mutations found in neuroblastoma." (PMID 27483357, 2016). "It is a frequent somatic mutation in neuroblastoma and increases ALK's affinity for ATP, despite not directly contacting the ATP pocket." (PMID 27009859, 2016). "Mutant ALK in neuroblastoma has increased kinase activity compared to wild-type ALK." (PMID 26771642, 2016). "However, clinical trials reveal that a limited proportion of ALK-positive neuroblastoma patients experience clinical benefits from Crizotinib, a clinically approved specific inhibitor of ALK." (PMID 27732954, 2016). "Therefore, targeting kinase activating mutant ALK using a molecular approach is expected to improve the clinical outcomes of advanced ALK mutant neuroblastoma." (PMID 26802023, 2016). "Hence, there is a great need for a more complete understanding of the downstream signaling pathways by which aberrant ALK signaling functions in neuroblastoma." (PMID 27732954, 2016). "Other relevant patient groups are young neuroblastoma patients, as well as other pediatric cancer patients with ALK driven cancers, that may take ALK inhibitors on a long-term basis." (PMID 25955180, 2015). "Furthermore, we found the reported strong expression of FAM150B in the human adrenal gland intriguing, given the role of ALK in neuroblastoma." (PMID 26418745, 2015). "These lines represent MYCN-amplified, NRAS and ALK mutant neuroblastoma subtypes respectively." (PMID 26517508, 2015). "ALK was detected in 22 distinct phosphopeptides in neuroblastoma samples, which could be collapsed into 13 distinct phosphorylation sites based on sequence homology." (PMID 25884760, 2015). "Tumours bearing ALK gene translocations, amplification or activating point mutations, other than ALCL, have been also identified, including non-small cell lung cancer (NSCLC), Inflammatory Myofibroblastic Tumour (IMT) and neuroblastoma." (PMID 25874976, 2015). "This is particularly important for ALK IHC-positive but ALK copy number/mutation-negative neuroblastomas, in which the utility of ALK targeted therapeutics is at present unascertained." (PMID 25188507, 2014). "With a recent phase 1 trial documenting complete response to the ALK inhibitor crizotinib in two patients with neuroblastomas, it seems probable that ALK status (whether protein, genomic or both) will emerge as a routine biomarker in neuroblastoma diagnostics." (PMID 25188507, 2014). "Correlation between ALK D5F3 IHC and hotspot mutational analysis results revealed that the majority of ALK D5F3 IHC-positive neuroblastomas did not possess the hotspot mutations." (PMID 25188507, 2014). "For neuroblastoma cell lines not known to harbor an ALK mutation, we used genotyping of short tandem repeats (STRs) at 11 loci." (PMID 25133137, 2014). "In our earlier analysis, we observed ALK expression in only 1/54 (1.85%) of neuroblastomas." (PMID 25188507, 2014). "Overexpression of ALK is often observed in human neural tumors, primarily neuroblastoma." (PMID 23667670, 2013).